BRCA1 (BRCA1 DNA repair associated)
Diseases named in the same sentence as BRCA1 in open-access papers (continued):
Sharing a sentence is not in itself a finding about the gene and the disease.
breast cancer (continued). "The role of ATF1 in breast cancer has been identified as a tumor suppressor, including its activation by BRCA1, increasing transcription of MHC class genes and its involvement in regulating the steroidal hormone synthesis (Haakenson, Kester & Liu, 2012)." (PMID 37810779, 2023). "The distribution of BRCA1 methylation was determined among the intrinsic subtypes of breast cancers, based on their mRNA signatures." (PMID 38053165, 2023). "Sixty studies included women with a positive family history of breast cancer (FHBC) and 3 additional studies included women with BRCA1/2 mutations and women with FHBC for a total of 63 studies." (PMID 37095519, 2023). "Although inactivation of BRCA1 is a key driver of many breast cancers, counter-intuitively, the initial biological effects of BRCA1 inactivation can be haploinsufficient induction of senescence or HIS." (PMID 37627161, 2023). "Studies revealed that BRCA1/2-intact breast cancer cells treated with PARP inhibitors reduce ribosome biogenesis and cell growth." (PMID 37564214, 2023). "T2DM development was seen in BRCA1/2 carriers even in a mean of 8.6 years after breast cancer diagnosis due to the chemotherapy and high BMI value." (PMID 37510134, 2023). "The study revealed the co-occurrence of BRCA1/2 in 13 breast cancer samples (log2 odds ratio: > 3, p-value < 0.001, and q-value < 0.001)." (PMID 38098088, 2023). "Mutations in BRCA1 and BRCA2 have not only been associated with an increased risk of breast cancer as they were later also found to increase susceptibility to ovarian, pancreatic, and prostate cancers." (PMID 37509303, 2023). "Mutations in either of the type 1 or 2 breast cancer susceptibility genes (BRCA1 and BRCA2) account for the majority of hereditary breast cancers." (PMID 37176102, 2023). "Our study depicted the mutational patterns of BRCA1, BRCA2, and PALB2 in Taiwanese breast cancer patients through tumor-only sequencing." (PMID 38098088, 2023). "We compared our model to scarHRD38 which uses WES to distinguish between BRCA1/2 mutant and BRCA1/2 wild type breast cancer." (PMID 36914848, 2023). "Recent reports suggest that population-based polygenic risk scores are strongly associate with breast cancer and EOC risks for BRCA1/2 carriers and predict significant differences in absolute risk for women at polygenic risk score distribution extremes." (PMID 38012622, 2023). "It favours the proliferation of breast cancer cells by repressing tumour suppressor genes such as BRCA1 and HOXA5." (PMID 37187521, 2023). "The BRCA1 mutant breast cancer cell line HCC1937 was used for in vitro experiments to assess the impact of PAF-AH on cellular functions." (PMID 36614323, 2023). "The ER-negative PREDICT-algorithm overestimated breast cancer mortality in all BRCA1/2 patient groups with ER-negative breast cancer from CIMBA and BCAC." (PMID 37173335, 2023). "Recently, gene screening data by next-generation sequencing (NGS) has demonstrated hereditary associations involving BRCA1/2, CDH1, BRIP1, and PTEN between breast cancer and ovarian cancer." (PMID 36810560, 2023).
breast cancer (continued). "The discovery of BRCA1 and BRCA2 pathogenic variants in women with breast cancer in the 1990s paved the way for the expansion of personalized cancer care." (PMID 37623478, 2023). "The Qatari National Center for Cancer Care and Research (NCCCR) genetic screening program uncovered 90 VUS in 78 patients with breast cancer; 29 patients with 36 BRCA1 VUS and 49 patients with 54 BRCA2 VUS." (PMID 37335020, 2023). "In contrast, mammary tumors form in aging mice where the Brca1 gene is conditionally deleted using the MMTV-Cre or WAP-Cre transgenes." (PMID 38067308, 2023). "Although TLZ was approved for treatment of metastatic germline BRCA1/2 breast cancer in 2018, expansion of approval to other malignancies has been hindered due to the more potent side effects associated with the drug." (PMID 37228496, 2023). "These include mutations in genes BRCA1 and BRCA2, associated with a 50-85% lifetime risk of breast cancer." (PMID 37750138, 2023). "Inherited deleterious variants in BRCA1 and BRCA2 genes are highly penetrant for HBOC, with lifetime risks (dependent upon the gene and population) up to 57% for breast cancer and up to 40% and 18% for ovarian cancer for BRCA1 and BRCA2 carriers, respectively." (PMID 36833429, 2023). "Our results established that BRCA1/2 plasmids incorporated into CA NPs mitigated breast tumor growth, signifying their application in the therapy for breast cancer." (PMID 36631481, 2023). "The molecular subtypes with the highest BM incidence are EGFR-mutated NSCLC and BRCA1, TN, and HER2+ breast cancers." (PMID 37484759, 2023). "They found that diverse and often polyclonal putative BRCA1 or BRCA2 reversion mutations were identified in cfDNA from four OC patients (21%) and two breast cancer patients." (PMID 37426808, 2023). "The molecular subtypes with the highest BM incidence are epithelial growth factor receptor-mutated non-small cell lung cancer (NSCLC), BRCA1, triple-negative (TN), and HER2+ breast cancers, and BRAF-mutated melanoma." (PMID 37484759, 2023). "Genetic predisposition accounts for 5–10% of all breast cancers, primarily attributed to pathogenic variants in BRCA1 and BRCA2 genes, responsible for nearly 90% of hereditary breast cancers." (PMID 38017478, 2023). "Breast Cancer 1 gene (BRCA1) and Breast Cancer 2 gene (BRCA2) are included in the category of high penetrance genes." (PMID 37055759, 2023). "Inherited mutations in high penetrance breast cancer susceptibility genes such as BRCA1 and BRCA2 are associated with relatively high lifetime breast cancer risk." (PMID 37043488, 2023). "Recent studies have further explored BRCA1’s role in breast cancer development and its profound impact on cellular differentiation." (PMID 37762577, 2023). "The use of Poly ADP Ribose Polymerase (PARP) inhibitors (PARPi) has radically improved the treatment outcomes of BRCA1/2mutation (mut) breast cancer patients." (PMID 36831687, 2023). "This was similar to a previous study in Korea finding 22.1% of BRCA1/2 carriers with bilateral breast cancer." (PMID 35778884, 2023). "Breast cancer is often driven by the upregulation of the Her2 oncoprotein or inactivation of the BRCA1 tumor suppressor." (PMID 37627161, 2023). "Another study showed that miR-218, which targets BRCA1, was downregulated in cisplatin-resistant breast cancer cell lines and, interestingly, the restoration of miR-218-sensitized MCF-7 breast cancer cells to this drug." (PMID 38132441, 2023). "But known risk genes (BRCA1/BRCA2 and others) are insufficient to explain all inherited breast cancer risk." (PMID 36702877, 2023). "As the saga of BRCA1’s contributions unfolds, these early revelations anchor our journey toward unraveling the intricate tapestry of breast cancer biology." (PMID 37762577, 2023).
breast cancer (continued). "For example, PI3K inhibitors have synergistic therapeutic effects if associated with PARPi in BRCA1-deficient breast cancer models, with the PI3K/AKT pathway being constitutively active in BRCA1-defective human cancer cells." (PMID 36980956, 2023). "The mean age at diagnosis of breast cancer was 42.0 ± 10.3 years (BRCA1, 39.8 ± 7.4 years; BRCA2, 46.2 ± 16.0 years)." (PMID 35778884, 2023). "Taken together, we consider these findings to validate and justify the use of WBC BRCA1 methylation as a marker of constitutional methylation in most individuals, including patients diagnosed with their primary breast cancer." (PMID 38053165, 2023). "STING activation is closely associated with DDR, and breast cancer often exhibits DDR-related gene alterations, particularly in BRCA1 or BRCA2 genes." (PMID 37448962, 2023). "Expression of estrogen receptor (ER), progesterone receptor (PR), human epidermal growth factor receptor 2 (HER2) and BRCA1 tumor suppressor protein in breast cancer cell lines described in this review." (PMID 37768037, 2023). "BRCA1/2 are the most common genes involved in HBOC, and mutations in either of the BRCA genes increase a woman’s risk of breast cancer to 45–65% by 70 years old." (PMID 38136308, 2023). "In recent years, the importance of different genetic markers in breast cancer has also been highlighted, with the importance of BRCA1 and BRCA2 standing out." (PMID 37176102, 2023). "Further, it has shown that BRCA1 and BRCA2 genetic mutations identified are of clinical relevance and there is a need to screen for these mutations in breast cancer patients to understand their implication in patient management outcomes." (PMID 37719058, 2023). "Two key factors associated with a high risk of breast cancer are mutations in the BRCA1 and BRCA2 (Breast Cancer; OMIM 113705 and OMIM 600185, respectively) genes, with the majority of hereditary cases attributed to the BRCA1 gene." (PMID 37147448, 2023). "When breast cancer cells and MSCs were simultaneously co-cultured, the therapeutic impact was diminished in vivo due to the upregulation of resistance-related genes (such as MUC1, MYC and BRCA1) in the breast cancer cells after cisplatin pre-treatment." (PMID 37569598, 2023). "Germline mutations of breast cancer susceptibility gene BRCA1 and BRCA2 (gBRCA1/2) are associated with elevated risk of breast cancer in young women in Asia." (PMID 36604691, 2023). "Here we examined the impact of two traditional markers of hereditary cancer risk (age at breast cancer diagnosis and family cancer history) on the risk of carrying a PV in the most commonly mutated breast cancer-risk genes: ATM, BRCA1, BRCA2, CHEK2, and PALB2." (PMID 37084156, 2023). "In recent years, “olaparib” and “double-blind” burst from 2020 to 2022, denoting the evaluation of the efficacy and safety of Olaparib in both monotherapy and combination therapy among patients with BRCA1/2-mutant breast cancer." (PMID 37476378, 2023). "Consistent with a role for IRX5 as a promoter of DNA damage repair, we find that IRX genes are upregulated in many cancer types and that there is a correlation between IRX5 and BRCA1 expression in breast cancer." (PMID 37084727, 2023). "BRCA1 and BRCA2 were the first two genes identified as having been associated with increased risk for breast cancer, when there is a mutation of either one." (PMID 37181043, 2023). "Among participants with family history of breast cancer, PTVs in ATM (p-value = 0.002), BRCA2 (p-value = 0.005), BRCA1 (p-value = 0.046), PALB2 (p-value = 0.039) and RAD50 (p-value = 0.044) were significantly associated with increased risk of breast cancer." (PMID 37790698, 2023).
breast cancer (continued). "This review presents a comprehensive overview concerning the design, development, and applications of electroanalytical methods of detection of nucleic acid breast cancer biomarkers, particularly miRNAs and BRCA1." (PMID 37112468, 2023). "For example, GATA3 acts as a downstream gene of BRCA1 to inhibit epithelial mesenchymal transition in breast cancer cells." (PMID 36468944, 2023). "Inherited mutations in breast cancer 1 and 2 (BRCA1 and 2) are detected in 11–20% of TNBC and 5–7% of all types of breast cancer cases and are the most common hereditary defect in breast cancer." (PMID 37759706, 2023). "It has been reported that Olaparib is an oral poly (ADP-ribose) polymerase inhibitor with activity in germline BRCA1 and BRCA2 (BRCA1/2)-associated breast cancers." (PMID 36906594, 2023). "The most common cancer detected during follow-up was breast cancer for both BRCA1 and BRCA2 groups and endometrial cancer for the BRCA-wt group." (PMID 38067403, 2023). "The authors identified protein-truncating variants in BRCA1, BRCA2, CHEK2, PALB2 and ATM that were significantly associated with breast cancer risk." (PMID 37662839, 2023). "The majority of BRCA1/2 mutant breast cancers are TNBC but only 10–15% of TNBC patients have inherited mutations in BRCA1/21." (PMID 37582853, 2023). "Inherited mutations in BRCA1 and BRCA2 predispose individuals to high risks of breast and ovarian cancers, with lifetime risks of breast cancer as high as 80% in the US." (PMID 37370892, 2023). "This increase is similar in magnitude to BRCA1 and BRCA2 gene variants and breast cancer risk, which are far less common (prevalence of 0.2–0.3%) and trigger more frequent cancer screening." (PMID 36651198, 2023). "We found that this operation was not linked with a reduced risk of developing breast cancer when considering both BRCA1 and BRCA2 carriers together but was linked with a reduced risk of breast cancer when considering BRCA2 carriers alone." (PMID 36900415, 2023). "This stage mainly explored the mutations of breast cancer-associated genes, including BRCA1/2, PALB2, and so on, through sequencing technology and the risk of breast cancer." (PMID 37476378, 2023). "The data presented here showed that the presence of familial breast cancer was more strongly associated with PV carrier status for ATM, BRCA1, BRCA2, CHEK2, and PALB2, in affected women (similar to previous studies)." (PMID 37084156, 2023). "HERC2-mediated breast cancer gene 1 (BRCA1) degradation is involved in DNA double-strand breaks repair, thereby enhancing breast cancer cell proliferation." (PMID 36721234, 2023). "BRCA1 and BRCA2 gene mutations are inherited and increase the likelihood of developing mammary tumors from early adulthood." (PMID 37835752, 2023). "Various resistance mechanisms, other than BRCA1/BRCA2 reversion mutations, have been reported in ovarian and breast cancer; however, there have been few reports on prostate cancer." (PMID 37174127, 2023). "Individuals with mutations in the BRCA1 and BRCA2 (BRCA1/2) genes have a significantly higher risk of developing various types of cancers, especially cancers of the breast, ovary, pancreas, and prostate." (PMID 37035242, 2023). "Especially in the Asian populations, gBRCA1/2-associated breast cancer are known to develop in younger age, with higher incidence of germline BRCA2 (gBRCA2) mutation than germline BRCA1 (gBRCA1) when compared to other ethnicities." (PMID 36604691, 2023). "Mutations in the BRCA1 and BRCA2 genes were shown to be associated with a risk of 60–85% of developing breast cancer." (PMID 37626804, 2023). "The HRR signature is strongly associated with germline and somatic mutations in BRCA1 and BRCA2 mutations in human breast cancer." (PMID 37805590, 2023). "PDGFRβ blockade was also reported to dampen BRCA1-mediated tumorigenesis in a transgenic mouse model of breast cancer." (PMID 37294349, 2023).
breast cancer (continued). "According to limited published data, almost 10–15% of breast cancer occurrences are inherited with the most commonly identified genetic alterations in BRCA1/2." (PMID 37400873, 2023). "Mean ages at breast cancer diagnosis of BRCA1, BRCA2, and non‐carriers were 39.8, 46.2, and 42.0 years, respectively." (PMID 35778884, 2023). "Affected women with a familial breast cancer diagnosed ≤ 45 years of age were about 3-times more likely to carry a PV in BRCA1 compared to those with familial breast cancer diagnosed > 45 years (OR 3.29, 95% CI 2.95, 3.67)." (PMID 37084156, 2023). "ETS1 is reported to up-regulate PARP1 in Ewing sarcoma and ovarian cancer, while ETS1 and ETS2 repress BRCA1 in breast cancer." (PMID 36814284, 2023). "Under normal circumstances, BRCA1 and BRCA2 are typical tumor suppressor genes, which means that people with BRCA1 and BRCA2 genetic defects are highly susceptible to breast cancer." (PMID 36765522, 2023). "ISG15 depletion significantly reduces cell proliferation rates in human BRCA1-mutated triple-negative, whereas its upregulation results in increased resistance to the chemotherapeutic drug cisplatin in mouse BRCA2-deficient breast cancer cells, respectively." (PMID 37783689, 2023). "Of relevance to young women, who are more likely to harbour germline BRCA1/2 mutations, are emerging data on the use of poly(ADP-ribose) polymerases (PARPs) inhibitors in early-stage breast cancer." (PMID 37046584, 2023). "Previous studies have found that RNF168 expression is decreased in various BRCA1-mutant cancer cell lines and primary tumors, such as breast cancer and ovarian cancer." (PMID 36771081, 2023). "BRCA1 and BRCA2 pathogenic variants account for 90% of hereditary breast malignancies, incurring a lifetime breast cancer risk of 85% and 40–45% respectively, in affected individuals." (PMID 38017478, 2023). "Although mutations of the BRCA1 and BRCA2 genes can cause hereditary cancers, they are extremely rare in sporadic breast cancers." (PMID 37509303, 2023). "To date, BRCA1 and BRCA2 are the most common and widely studied breast cancer susceptibility genes, accounting for up to 40% of familial breast cancer." (PMID 36980802, 2023). "Overall, these results suggest a functional BRCAness phenotype in the BRCA1/2-wt ER+ breast cancer cells upon SOC treatment that precedes SOC-induced G1 arrest." (PMID 37914699, 2023). "After controlling for family history, women diagnosed with breast cancer ≤ 45 years of age were nearly four times more likely to carry a BRCA1 PV than those diagnosed > 45 years (OR 3.95, 95% CI 3.64–4.29)." (PMID 37084156, 2023). "High to moderate penetrant mutations in breast cancer predisposition genes, such as BRCA1 and BRCA2, are rare in large populations and account for only 5–10% of total breast cancer cases." (PMID 36315068, 2023). "Specific gene mutations, such as mutations in the BRCA1 and BRCA2 genes, significantly increase the risk of developing breast cancer." (PMID 37575755, 2023). "Pathogenic variants in the BRCA1 and BRCA2 genes are responsible for approximately 20% of hereditary breast cancers." (PMID 37239898, 2023). "In the present work, we evaluated the associations of height, BMI, and change in weight with pre- and postmenopausal breast cancer risk for carriers of a pathogenic variant in BRCA1 or BRCA2, using data from the International BRCA1 and BRCA2 Cohort Consortium." (PMID 37340476, 2023). "Another study has shown that YY1 positively induces expression of BRCA1, a tumor suppressor, leading to tumor inhibition in breast cancer." (PMID 37444605, 2023).